PHB2 (prohibitin 2)
Diseases named in the same sentence as PHB2 in open-access papers (continued):
Sharing a sentence is not in itself a finding about the gene and the disease.
Sepsis (5 papers, 2023 to 2025). Sepsis is defined as life-threatening organ dysfunction caused by a dysregulated host response to infection. "In summary, our findings illuminate that a deficiency in PKM2 and PHB2 contributes to the dysregulation of mitochondrial quality control during LPS-induced sepsis, implicating these proteins as key modulators in septic myocardial and cerebral injuries." (PMID 38464826, 2024). "Despite these limitations, our study demonstrates that Nrf2 increased PHB2 expression to prevent mitochondrial damage in ALI associated with SA‐sepsis." (PMID 38077250, 2023). "The use of gene therapy to overexpress PKM2 and PHB2 in susceptible patient populations, such as those with a history of sepsis or at high risk of developing septic complications, could be explored." (PMID 38464826, 2024). "IGFBP6 orchestrates sepsis pathogenesis via PHB2-dependent immunosuppression and macrophage dysfunction, establishing it as a diagnostic-therapeutic nexus." (PMID 40892465, 2025). "To investigate alterations in PKM2 and PHB2 expressions in cardiac and cerebral tissues following sepsis, we utilized a lipopolysaccharide (LPS)-induced mouse model." (PMID 38464826, 2024). "The compelling evidence provided by this study on the protective roles of PKM2 and PHB2 in mitigating sepsis-induced mitochondrial dysregulation opens new avenues for clinical intervention strategies." (PMID 38464826, 2024). "Employing LPS-induced mouse models, we demonstrate a significant downregulation of PKM2 and PHB2 in both heart and brain tissues post-sepsis, with corresponding impairments in mitochondrial dynamics, including fission, fusion, and mitophagy." (PMID 38464826, 2024). "In a bid to extend our in vitro observations to an in vivo model, we engineered PHB2 transgenic (PHB2Tg) mice and subjected them to LPS-induced sepsis." (PMID 38464826, 2024). "Intriguingly, our in vivo findings reveal that PKM2 and PHB2 transgenic mice exhibit resilience to sepsis-induced cardiac and cerebral dysfunction." (PMID 38464826, 2024). "Recent research focusing on the role of prohibitin 2 (PHB2) in sepsis-induced cardiomyopathy and inflammatory cardiomyopathy has yielded significant insights into the molecular mechanisms underlying these conditions." (PMID 38774750, 2024). "Overall, our findings provide compelling evidence that PHB2 overexpression mitigates the detrimental effects of sepsis on myocardial and cerebral functions, suggesting a potential therapeutic strategy for sepsis-induced organ dysfunction." (PMID 38464826, 2024). "These cellular mechanisms translate into substantial in vivo benefits, with transgenic mice overexpressing PKM2 or PHB2 displaying remarkable resistance to sepsis-induced cardiomyocyte and neuronal apoptosis, and organ dysfunction." (PMID 38464826, 2024). "By influencing the selective degradation of damaged mitochondria, PHB2 ensures cellular homeostasis, a vital aspect in sepsis where cellular debris and dysfunction can exacerbate injury." (PMID 38464826, 2024). "Our research demonstrated the significance of Nrf2 as a crucial transcription factor in sepsis, and notably, Nrf2 exhibited enrichment when PHB2 was employed as input." (PMID 38077250, 2023). "(c) PHB2/STAT1/CCL2 axis modulation reverses IGFBP6-mediated sepsis pathology." (PMID 40892465, 2025). "Studies suggest that PKM2 may impact sepsis-induced cardiomyopathy through interactions with molecules and pathways, such as prohibitin 2 (PHB2)." (PMID 38774750, 2024). "A comprehensive understanding of the intricate relationship between PHB2 and mitochondria holds promise for shedding light on the pathogenesis of diverse disorders, such as sepsis-induced cardiomyopathy, and unveiling potential therapeutic targets for intervention." (PMID 38774750, 2024).
Sepsis (continued). "The observed downregulation of PKM2 and PHB2 at both transcriptional and protein levels post-sepsis suggests that these molecules may be sensitive indicators of septic stress in cardiac and cerebral tissues." (PMID 38464826, 2024). "Furthermore, investigations have highlighted the regulatory role of PHB2 in cellular stress responses and apoptosis, indicating its potential in safeguarding cardiac cells from damage in pathological conditions such as sepsis and inflammation." (PMID 38774750, 2024). "Thus, exploring the multifaceted roles of PHB2 in the context of septic cardiovascular and cerebrovascular damage opens new avenues for understanding the pathophysiology of sepsis." (PMID 38464826, 2024). "Furthermore, clinical trials are imperative to assess the efficacy of modulating PKM2 and PHB2 expressions as a therapeutic intervention for sepsis." (PMID 38464826, 2024). "Given the downregulation of PKM2 and PHB2 during sepsis, these proteins could serve as biomarkers for early detection and the progression of septic injury." (PMID 38464826, 2024). "Our findings demonstrate that sepsis induces a profound suppression of PKM2 and PHB2, corroborating their roles as mitochondrial protectants and signaling entities." (PMID 38464826, 2024). "Collectively, these findings unequivocally demonstrate that sepsis, induced via LPS, leads to a significant downregulation of PKM2 and PHB2 in both heart and brain tissues." (PMID 38464826, 2024). "In conjunction with standard sepsis treatments, drugs targeting PKM2 and PHB2 could be part of a combination therapy approach." (PMID 38464826, 2024).
cholestasis (4 papers, 2018 to 2023). Impairment of the bile flow caused by obstruction within the liver, or outside the liver in the bile duct system. "Mechanistically, we find that the prohibitin 2 (PHB2) is crucial for cholestasis-mediated mitophagy in vitro." (PMID 29416008, 2018). "Our findings demonstrate that PHB2 is required for cholestasis-induced mitophagy in which PHB2 brings LC3 to the damaged mitochondria via interaction with SQSTM1and LC3." (PMID 29416008, 2018). "Our study suggests that the PHB2 is involved in cholestasis-mediated mitophagy via recruitment of the autophagosomal membrane-associated protein LC3 onto the damaged mitochondria." (PMID 29416008, 2018). "Altogether, our study suggests that PHB2 is required for cholestasis-induced mitophagy via LC3 onto the injured mitochondria." (PMID 29416008, 2018). "Furthermore, PHB2 is also required for cholestasis-induced mitophagy via LC3 into the injured mitochondria." (PMID 37958902, 2023). "Also, it was reported that PHB2 is required for cholestasis-induced mitophagy, where PHB2 brings LC3 to the damaged mitochondria by interacting with p62 and LC3." (PMID 34580273, 2021). "Furthermore, it has been suggested that PHB2 is required for cholestasis-induced mitophagy, wherein PHB2 recruits LC3 to the damaged mitochondria via interaction with p62/SQSTM1 and LC3." (PMID 32751272, 2020). "In conclusion, we suggest that PHB2 is essential to cholestasis-induced mitophagy in the cholestatic liver via directly binding the LC3 and may interact with SQSTM1 to recruit LC3 into the impaired mitochondria." (PMID 29416008, 2018). "We next assessed the effects of PHB2 in cholestasis-mediated mitophagy." (PMID 29416008, 2018).
colorectal cancer (4 papers, 2022 to 2025). A primary or metastatic malignant neoplasm that affects the colon or rectum. "In addition, some cancers (colorectal cancer) are associated with a marked increase in PHB1 and PHB2 levels in blood serum." (PMID 38813101, 2024). "It is known that PHB2 can interact with NDUFS1 to stabilize the mitochondrial complex I and to enhance its activity in human colorectal cancer cells." (PMID 40828869, 2025).
lung carcinoma (4 papers, 2016 to 2023). "As expected, RACK1 could be ubiquitinated in lung cancer cells, and PHB2 overexpression reduced RACK1 ubiquitination." (PMID 33537079, 2021). "Interestingly, the KM Plotter analysis showed that PHB2 expression was negatively correlated with overall survival (OS) in patients with lung cancer, and a similar result was observed in patients with lung adenocarcinoma." (PMID 33537079, 2021).
neuroblastoma (4 papers, 2022 to 2024). Neuroblastoma (NB) is the most common solid, extracranial childhood tumor. "Artemisinin, known for its powerful antioxidative stress effect, alleviated oxidative damage caused by cerebral ischemia/reperfusion by regulating PHB2-mediated autophagy in the human neuroblastoma SH-SY5Y cell line." (PMID 37958902, 2023). "This pattern was replicated in N2a neuroblastoma cells subjected to LPS treatment, with a marked decrease in PKM2 and PHB2 protein levels relative to baseline conditions." (PMID 38464826, 2024).
pancreatic cancer (4 papers, 2015 to 2021). "MDA-MB-231 and PANC1, models for breast and pancreatic cancer, respectively, were transfected with siRNA knocking down PHB1 and PHB2." (PMID 29643415, 2018). "Recently, rocaglamide was found to selectively bind to PHB1 and PHB2 with nanomolar affinity and to influence the membrane localization of PHB1 and PHB2 in the human T cell leukemic cell line Jurkat, the human cervical cancer cell line HeLa and the pancreatic cancer cell line AsPC-1." (PMID 26091791, 2015). "In MiaPaCa-2 pancreatic cancer cells, Akt phosphorylates PHB1 at Thr258 but does not phosphorylate PHB2." (PMID 26091791, 2015).
prostate carcinoma (4 papers, 2021 to 2024). A carcinoma that arises from epithelial cells of the prostate gland. "Increasing evidence shows that PHB2 is highly expressed in prostate cancer 10, liver cancer 11, esophageal squamous cell carcinoma 12, and diffuse large B cell lymphomas 13 compared with normal tissues." (PMID 33537079, 2021). "PHB2 is known to promote prostate cancer (PCa) progression and is overexpressed in PCa." (PMID 37190120, 2023). "It was found that overexpression of PHB2 reduced AKT2 expression levels and knockdown of PHB2 increased the expression of AKT2 levels in prostate cancer cells." (PMID 37190120, 2023). "In human prostate cancer cells, PHB and PHB2 have tumor suppressor functions, and they interact with the E2F transcription factor family in the nucleus to reduce E2F function, causing cell cycle arrest in the G1/S phase." (PMID 37868974, 2023). "Apart from AKT as a target of PHB2 in prostate cancer and NSCLC, it was also reported as an upstream regulator of PHB2." (PMID 37190120, 2023).
cervical cancer (3 papers, 2015 to 2021). A primary or metastatic malignant neoplasm involving the cervix. "Similarly, phosphorylation level of CCNB1, CDC25C and CDK1 has been inhibited, then leading to G2/M phase arrest and cell apoptosis, suggesting that Lm-PHB2 may have therapeutic value in the treatment of cervical cancer." (PMID 29500418, 2018).
diabetic cardiomyopathy (3 papers, 2022 to 2024). Diabetic cardiomyopathy is a disorder of the heart muscle in people with diabetes. "Our research endeavors to elucidate the roles of Pgam5 and Phb2 in modulating the evolution of diabetic cardiomyopathy and its underlying mechanisms." (PMID 38818468, 2024). "This study aims to elucidate the roles of Phosphoglycerate Mutase Family Member 5 (Pgam5) and Prohibitin 2 (Phb2) in the context of hyperglycemia-induced myocardial dysfunction, a critical aspect of diabetic cardiomyopathy." (PMID 38818468, 2024). "Firstly, while the study provides crucial insights into the roles of Pgam5 and Phb2 in diabetic cardiomyopathy, it primarily relies on in vitro models." (PMID 38818468, 2024).
glioma (3 papers, 2024 to 2025). A benign or malignant brain and spinal cord tumor that arises from glial cells (astrocytes, oligodendrocytes, ependymal cells). "In glioma stem-like cells (GSCs), PHB2 specifically regulates mitochondrial ROS production, contributing to radiotherapy resistance." (PMID 40076502, 2025). "Interestingly, it has been shown that GOLPH3 of human glioma U251 cells interacts with the cytosolic proteins PHB1 and PHB2, which have also been observed to be associated with mitochondria." (PMID 38391929, 2024). "Several studies have reported that GOLPH3 promotes autophagy in glioma cells via PHB2 but not PHB1." (PMID 40168274, 2025).
myocardial infarction (3 papers, 2020 to 2025). Gross necrosis of the myocardium, as a result of interruption of the blood supply to the area, as in coronary thrombosis. "LncRNA cardiac apoptosis-related lncRNA (CARL), regulates apoptosis by targeting miR-539 and PHB2 in mice with myocardial infarction." (PMID 31913855, 2020). "The prohibitin complexes PHB1 and PHB2, which are overexpressed in the mitochondrial inner membrane, control the reduction in apoptosis and myocardial infarct size, the equilibrium of mitochondrial dynamics in the heart during I/R injury being extremely important." (PMID 35269870, 2022).
B-cell neoplasm (2 papers, 2014 to 2015). A group of heterogeneous lymphoid tumors generally expressing one or more B-cell antigens or representing malignant transformations of B-lymphocytes. "Our study also discovered a number of candidate therapeutic targets for the treatment of B cell neoplasms, including NF-κB2, PKCδ, MCC, PARP1, and PHB2." (PMID 25960828, 2015). "Given the preclinical evidence that both PARP1 and PHB2/PHB1 are excellent therapeutic targets in human cancers, our findings also implicate potential applications of PARP inhibitors and PHB ligands in the treatment of B cell neoplasms involving TRAF3 inactivation or aberrant MCC expression." (PMID 25960828, 2015). "Since our new proteomic data identified PARP1 and PHB2/PHB1 as two signaling hubs of the novel oncoprotein MCC in human MM cells, we are currently testing the therapeutic efficacy of PARP1 inhibitors and PHB ligands in B cell neoplasms with TRAF3 inactivation or aberrant MCC expression." (PMID 25960828, 2015). "Furthermore, the central role of PARP1 and PHB2 in the MCC interaction network of human MM cells implies that PARP1 inhibitors and PHB ligands may have therapeutic application in B cell neoplasms, including NHL and MM." (PMID 25200342, 2014).
cardiomyopathy (2 papers, 2024). A disease of the heart muscle or myocardium proper. "The dysregulation of PHB2 in cardiomyopathies has underscored its promise as a therapeutic target for ameliorating mitochondrial dysfunction and enhancing cardiac outcomes in septic and inflammatory scenarios." (PMID 38774750, 2024). "PHB2 has been shown to ameliorate DOX-induced cardiomyopathy by inhibiting interstitial fibrosis and restoring the mitochondrial complex I function by interacting with NDUFV2." (PMID 39507806, 2024).
colon carcinoma (2 papers, 2015 to 2023). "One study highlighted the important interaction between PHB2 and a specific lncRNA tied to colon cancer, Lnc34a." (PMID 37190120, 2023). "As discussed in colon cancer (Section 4.3), Lnc34a binds to PHB2 and forms a complex with DNMT3A, methylating the miR-34a promoter." (PMID 37190120, 2023). "Overexpression of PHB2 enhances colon cancer growth in vitro and in vivo." (PMID 37190120, 2023). "PHB2 was reported as a novel target of Dihydroartemisinin (DHA) in colon cancer." (PMID 37190120, 2023). "Therefore, both PHB2 and RCHY1 are promising targets in colon cancer therapy." (PMID 37190120, 2023).
diabetic nephropathy (2 papers, 2023 to 2025). "PHB2, expressed in the nucleus, mitochondria, and cytoplasm, has been noted to play crucial roles in models of various kidney injuries, such as diabetic nephropathy, angiotensin II-induced kidney injury, and ischemia–reperfusion injury." (PMID 41438218, 2025).
endotoxemia (2 papers, 2023 to 2025). "Based on in vitro and in silico analyses, we concluded that under endotoxemia conditions, Pgam5 directly interacts with PHB2 and induces PHB2 dephosphorylation at Ser39." (PMID 37781037, 2023). "Our findings thus identified the Pgam5/PHB2 interaction as a promising target for the treatment of endotoxemia-related cardiac dysfunction." (PMID 37781037, 2023). "We found that PHB2 transgenic mice are resistant to endotoxemia-mediated myocardial depression and mitochondrial damage." (PMID 37781037, 2023). "Herein, we report on the complex relationship between the mitochondrial serine/threonine-protein phosphatase Pgam5 and PHB2, a component of the mitochondrial prohibitin complex, in endotoxemia-mediated myocardial dysfunction." (PMID 37781037, 2023). "In light of this, it is of interest to assess the phosphorylation status of PHB2 during endotoxemia." (PMID 37781037, 2023). "In conclusion, our findings revealed that Pgam5-mediated dephosphorylation of PHB2 critically contributes to endotoxemia-related cardiac dysfunction by preventing PHB2 mitochondrial import, which is required for activation of both mitophagy and UPRmt." (PMID 37781037, 2023). "Importantly, our results showed that Pgam5-mediated dephosphorylation of PHB2-Ser39 is a novel pathological alteration that contributes to endotoxemia-mediated mitochondrial damage and cardiomyocyte death by preventing PHB2 mitochondrial recruitment." (PMID 37781037, 2023). "Since cardiomyocyte viability is closely dependent on normal mitochondrial function, we wondered whether PHB2 overexpression-mediated cardiomyocyte survival in endotoxemia results from preserved mitochondrial homeostasis." (PMID 37781037, 2023). "Although prohibitin 1 (PHB1) overexpression was found to attenuate sepsis-related cardiomyopathy through restoring the activity of the mitochondrial respiratory chain 33, 34, evidence for the precise role of PHB2 in endotoxemia-related myocardial depression is still lacking." (PMID 37781037, 2023).
gastric cancer (2 papers, 2021 to 2024). A primary or metastatic malignant neoplasm involving the stomach. "In this study, our aim is to explore the functional role of PHB2 and its underlying mechanisms in gastric cancer (GC)." (PMID 38200519, 2024). "We have now studied the role of FOLRα in gastric cancer and found that a signaling axis comprising FOLRα, prohibitin 2 (PHB2), and murine double minute 2 (MDM2) contributes to chemotherapy resistance." (PMID 34185411, 2021).